LEP (leptin)
Diseases named in the same sentence as LEP in open-access papers (continued):
Sharing a sentence is not in itself a finding about the gene and the disease.
cancer (continued). "We speculate that leptin may further stimulate proliferation and tumorigenesis by down-regulating cancer cell XOR." (PMID 23369448, 2012). "Adipokines such as adiponectin, leptin, and hepatocyte growth factor may regulate cancer cell proliferation and may be related to cancer progression." (PMID 22778714, 2012). "The increase in the adiponectin:leptin ratio and thus, the balance between these adipokines in EE mice may have limited cancer cell growth in this group." (PMID 23272114, 2012). "In both animal and human models, circulating leptin levels decrease in the setting of cancer-ACS." (PMID 22518191, 2012). "Leptin is thought to play a major role in the pathophysiology of cancer-ACS." (PMID 22518191, 2012). "Leptin is known as a proliferative and antiapoptotic agent in many cancers." (PMID 21991326, 2011). "In addition, a significant difference (P < 0.05) was observed between the leptin hormone levels in males and females in both healthy and cancer groups." (PMID 22007338, 2011). "In addition if the leptin levels in cancer patients decrease after thyroidectomy, it will be used for the followup treatment, possibly." (PMID 22007338, 2011). "However, until today, this complex interplay between leptin, immune system, and cancer has received only some experimental support and further investigations are required." (PMID 21040518, 2010). "Studies have led to the hypothesis that leptin contributes in cancer development, at least in part, through its up-regulatory role in the inflammatory system." (PMID 21040518, 2010). "Leptin's pleiotropic actions may therefore impact the growth of cancer through a variety of mechanisms." (PMID 19531256, 2009). "In addition, leptin and adiponectin have been adipocytokines that attracted attention for cancer research." (PMID 21566743, 2008). "Also, three cancer-associated proteins, GRO, LIF, TIMP-2 were also down-regulated, along with Leptin, an energy intake and expenditure regulator." (PMID 18282300, 2008). "Contrary, in breast cancer in situ, leptin does not appear to increase the risk of pre-menopausal cancer." (PMID 21566743, 2008). "In addition, both leptin and its receptors have been elevated in cancer tissue compared with normal tissue." (PMID 21566743, 2008). "Recent findings support the hypothesis that cytokineinduction of leptin may play a significant role in anorexia andcachexia of inflammatory diseases and cancer." (PMID 17497033, 2007). "Leptin concentrations remained stable in the control (P=0.186) and cancer (P=0.062) groups." (PMID 15026790, 2004). "Moreover, cancer cells and the tumour microenvironment expressing leptin and leptin receptors suggest that the potential leptin autocrine/paracrine signalling loop could affect tumour progression." (PMID 39941741, 2025). "In addition to alterations in adiponectin and leptin levels, elevated levels of other adipokines, such as resistin, interleukin‐6 (IL‐6), and tumor necrosis factor‐alpha (TNF‐α), are associated with an increased risk of cancer." (PMID 40620232, 2025). "In cancer, unlike starvation, reduced leptin and elevated ghrelin do not increase appetite, indicating a central neurohormonal imbalance that might explain cancer-associated anorexia." (PMID 41373996, 2025). "In humans, a recent cross-sectional observational study enrolling 624 adults in the American Cancer Society’s Cancer Prevention Study-3 Diet Assessment Substudy found a positive association between the consumption of artificial NNSs, including ASP, SAC, SUC, and Ace-K, and leptin, CRP, and IL-6." (PMID 41156503, 2025). "High subcutaneous adiposity leads to elevated leptin levels (hyperleptinemia), a condition that promotes the secretion of inflammatory factors and further activates immune cells, thus affecting the tumor immune microenvironment and supporting cancer cell growth and migration." (PMID 40165893, 2025).
cancer (continued). "Thus, the disturbed balance of PRAT-derived leptin and adiponectin, added to other adipokines, may support cancer cell growth in the tumor microenvironment, especially in obese patients." (PMID 40227577, 2025). "In addition to these pro-angiogenic effects, leptin also regulates adipocyte capillary fenestration, resulting in vessels that may become more permeable to cancer cell extravasation and metastasis." (PMID 39439572, 2024). "Importantly, leptin-induced mitochondrial metabolism promoted cancer cell migration." (PMID 38228661, 2024). "In addition, we noted that in the presence of cancer, the microenvironment (Nw-MA+M0+Tumoroids vs Nw-MA+M0) shifted in the opposite direction to dim 2 with significant decreases in adiponectin levels and increases in IL-8, IL-23, and leptin secretion." (PMID 39072314, 2024). "However, the impact of leptin varies depending on the specific cancer type." (PMID 39518143, 2024). "Overall, increased amounts of leptin have been attributed to tumorigenic characteristics while decreased amounts of adiponectin are tied to a lack of activated anti-tumor pathways playing an influential role in the crosstalk between dysregulated adipose tissue and cancer." (PMID 39596205, 2024). "Leptin is involved in the expression of matrix metalloproteinases, the activation of the transforming growth factor-β signaling pathway, and the engagement in the process of the epithelial–mesenchymal transition, all of which are crucial for cancer cell migration." (PMID 38255203, 2024). "Thus, leptin may also increase the production of inflammatory proteins and growth factors that promote the growth and invasion of cancer cells." (PMID 37238961, 2023). "Finally, we showed that targeting p73γ or Leptin led to growth suppression of E11-KO xenografts in a mouse xenograft model, suggesting that the p73γ-Leptin pathway may be explored for cancer management." (PMID 37650871, 2023). "Leptin may have synergistic actions with other cytokines in different types of cancers." (PMID 36674935, 2023). "Cancers cells can reprogram adipocyte physiology leading to an “activated” phenotype characterized by delipidation and secretion of inflammatory adipokines such as IL-6, leptin and fatty acids which are able to change cancer cell metabolism and signalling pathways to promote tumour progression." (PMID 36790524, 2023). "Furthermore, it has also been evidenced that GBM cells consisting of vasculogenic mimicry (VM), the vascular channels lacking endothelial cells that are characterized by tumor cells with cancer stem cell features, were positive correlated with leptin expression and its receptor." (PMID 37509120, 2023). "Likewise, cancer cells affect leptin and VEGF synthesis in human adipose stem cells." (PMID 37686525, 2023). "Thus, the relationship between leptin, ObR and VM formation was examined in this cancer." (PMID 37686525, 2023). "Additionally, leptin is a growth factor and a direct physiological agent in cancer growth." (PMID 38068717, 2023). "Moreover, leptin may drive cancer progression in a hypoxic environment and when mitochondrial respiration is impaired by sustaining aerobic glycolysis, which can stimulate cancer survival in an adverse metabolic microenvironment by sustaining HIF-1α activity." (PMID 37686525, 2023). "In addition to its physiological role in the body, leptin affects cancer development." (PMID 37190027, 2023). "In addition, high plasma leptin levels may be correlated with the development of other types of cancer such as endometrial cancer, renal-cell carcinoma, thyroid cancers, and malignant melanoma." (PMID 37238961, 2023). "Moreover, SM significantly suppressed the leptin-associated phosphorylation of extracellular signal-regulated kinase 1/2 (ERK1/2) and ribosomal protein S6 kinase A1 (p90RSK), which are key kinases that ensure the survival and proliferation of cancer cells." (PMID 37895840, 2023).
cancer (continued). "Interestingly, during the development of obesity, pre-adipocytes differentiate incorrectly, and leptin levels increase, while adiponectin levels decrease, which is consistent with what occurs within CAAs to enable them to drive cancer progression." (PMID 37649895, 2023). "Therefore, researchers are investigating the effects of leptin on cytokines in cancer cells." (PMID 37155466, 2023). "The role of leptin in the regulation of Notch pathways has been well established in breast cancer, where, together with IL-1, Notch upregulates ligands, receptors, and relevant genes, thus enhancing the induction of proliferation and migration of cancer cells, as well as chemoresistance." (PMID 35628118, 2022). "Moreover, leptin stimulates cancer stem cells, which leads to cell proliferation and tumour growth." (PMID 35628118, 2022). "Similarly, these results may also explain the findings of our clinical research, as well as our mouse model of tumor growth, considering the cancer-promoting effects of leptin in our assays." (PMID 35778755, 2022). "Leptin stimulates NFκB, which may improve the survival of chemotherapy-treated cancer cells." (PMID 36556428, 2022). "Considering the similarities in the mechanisms between which leptin and ghrelin exert their effects on cancer cells as well as their observed inverse relationship, the interactions between ghrelin and leptin could prove an interesting point for future study in relation to cancer." (PMID 35454071, 2022). "Leptin, whose expression is elevated in overweight/obese individuals, promotes the production of oestrogen as a result of increased aromatase activity which may be related to the progression of oestrogen receptor-positive cancers." (PMID 36556428, 2022). "Similarly, the LEP gene was characteristic of G2 and G3 cancers in both cases." (PMID 34202922, 2021). "4-MTBITC treatment attenuated DMBA induced alteration in leptin (29% at p < 0.05) and adiponectin (52% at p < 0.01) levels compared to group B. It was observed that the levels of insulin were significantly increased (94% at p < 0.01) in cancer-bearing rats as compared to control." (PMID 34447314, 2021). "However, leptin may expand cancer cells through the production of cytokines by macrophages and also upregulate the pro-inflammatory cytokines such as TNF-α and IL-6 and stimulated the macrophage function." (PMID 34360753, 2021). "Moreover, leptin signaling may promote oncogenesis through the promotion of the cancer stem cell phenotype." (PMID 34202969, 2021). "Besides its well-known action as anorexigenic hormone, leptin stimulates pro-inflammatory cytokines production, promotes angiogenesis and acts as a growth factor in tumorigenesis, thus contributing to development of more aggressive cancers." (PMID 34205356, 2021). "Furthermore, given the role of mitochondria as a main source of cellular ROS, leptin-promoted autophagy may contribute to the control of redox balance in cancer cells." (PMID 33535537, 2021). "Therefore, the signaling pathways activated by leptin could have a direct influence on autophagy and the activation of autophagy could also possibly act as a feedback mechanism for the maintenance of cancer-related leptin signaling." (PMID 33763424, 2021). "Notably, among biomarkers related to cancer development, energetic interventions decreased serum leptin but increased serum adiponectin, suggesting that regulation of adipokine levels by exercise and body-weight control is associated with reduced carcinogenesis." (PMID 33535537, 2021). "Evidence has shown that GSK3 appears to be overexpressed in most cancer cells and that leptin increases the mRNA expression of hTERT through signal transducer and activators of transcription 3, suggesting a mechanism for an increased incidence of cancer in obese individuals." (PMID 34235021, 2021).
cancer (continued). "In addition, the binding leptin/Ob-Rb has been demonstrated to induce cancer progression via extracellular matrix-cell interactions, and epithelial−mesenchymal transition, an important step during metastasis to transform epithelial cells into mesenchymal cells." (PMID 34202969, 2021). "In sum, several studies support a role of leptin in tumorigenesis which favors cell growth and survival by increasing proliferation and decreasing apoptosis, regulating inflammatory processes, modulating cancer stem cell properties as well as metabolic activity." (PMID 33987528, 2021). "Leptin exerts pleiotropic functions so that, on the one hand, it increases insulin sensitivity in hepatocytes and, on the other, it promotes hepatic fibrosis via HSCs and can directly stimulate proliferation and antiapoptosis in cancer cells to augment cancer progression." (PMID 33671547, 2021). "Therefore, we can put forward a hypothesis that leptin confers metabolic plasticity to cancer cells that facilitates survival and proliferation under different growth conditions." (PMID 33535537, 2021). "Since leptin is a positive modulator of both the innate and the adaptive immune system, it may contribute to the increased immune response stimulated by immunotherapy in cancer patients and may be proposed as a good actor in cancer." (PMID 34202969, 2021). "Interestingly, while both leptin and adiponectin have been shown to activate autophagy, autophagy induction by these adipokines leads to opposite consequences on survival and proliferation of cancer cells." (PMID 33535537, 2021). "Several studies reported the development of compounds that interfere with leptin signaling (such as peptide antagonists, leptin protein mutants, monoclonal antibodies, nanobodies), and, thereby, can be used as potential drugs for the treatment of cancers and other diseases." (PMID 34356668, 2021). "Thus, dysregulation of signaling pathways of leptin and their receptors might be involved in the emergence of cancer." (PMID 32573960, 2020). "Leptin and adiponectin may exert antagonistic molecular effects on cancer progression." (PMID 32033341, 2020). "In line with the previous observations, excessive leptin may thus favor cancer cell migration." (PMID 33490070, 2020). "However, very few studies have evaluated alterations in ghrelin and leptin during chemotherapy in different types of cancer, and these discrepant results may be due to the different treatments adopted." (PMID 32491080, 2020). "Indeed, leptin works on two levels; on one hand, it modulates estrogen production in adipose stroma, and on the other hand, it induces upregulation of ER expression and ER functional transactivation in BC cells governing estrogen sensitivity in cancer cells." (PMID 32120856, 2020). "This review reported the findings of adipokines (leptin, adiponectin, resistin, apelin, and visfatin) in cancer cachexia, highlighting that to study in-depth the involvement of these hormones in this pathology could lead to the development of new therapeutic strategies." (PMID 32660156, 2020). "Finally, stimulation of epithelial-to-mesenchymal transition (EMT) is obtained with leptin and with thyroid hormone, suggesting that both factors may support cancer metastasis." (PMID 32645835, 2020). "Furthermore, leptin expression in metastatic cells may indicate that the carcinoma cells maintain their ability to produce the hormone in the new growth site or that they have internalized the hormone from the circulation or the microenvironment." (PMID 33213024, 2020). "Amongst these, chronic inflammation, higher secretion of leptin (accompanied by systemic leptin resistance) and lower adiponectin levels in obese subjects may deregulate cell division and angiogenesis and promote the development of cancer." (PMID 30658617, 2019).
cancer (continued). "However, despite some recent conclusions on obese patients and cancer, no report was yet published about the possible association of the SNP rs1137101 at the leptin gene." (PMID 30635060, 2019). "The differences in the mutation drivers may explain the different behavior of our PTC cells; however, such findings demonstrate that leptin mildly increases the aggressive phenotype of these cancer cells, which is in line with some previous studies on tumor cells of thyroid and breast origin." (PMID 30906321, 2019). "Hence, leptin signaling plays a stimulating role in the progression of various cancers." (PMID 30718259, 2019). "Therefore, we sought to investigate whether the cancer cells were able to penetrate a model barrier consisting of components of the basement membrane in response to leptin and FAK inhibition." (PMID 31671408, 2019). "For instance, leptin neutralization may improve cancer vaccination in obese individuals." (PMID 31340438, 2019). "Serum analysis of mice that developed cancer showed, in parallel with the others, increased insulin (z = +5.06, p < 1 × 10−4) and C-peptide levels (z = +4.42, p < 1 × 10−4) and decreased glucose and leptin levels (z = −2.89, p = 0.004 and z = −2.99, p = 0.003, respectively)." (PMID 29662006, 2018). "However, the therapeutic inhibition of IL-6- and leptin-evoked signaling via Stat3 inhibitors or rapamycin in cancer therapy might still be a challenge due to systemic effects." (PMID 30224299, 2018). "However, leptin regulation of glycolytic gene transcripts has been recently described in cancer cell lines, indicating this particular function of leptin is likely conserved across vertebrate taxa and may serve an important role in tumor bioenergetics." (PMID 30186233, 2018). "Moreover, the studies with regard to anti-leptin-dependent cancer metastasis was explored." (PMID 29682217, 2018). "Furthermore, emerging studies pointed out its expression in broad range of cancer types and also the leptin-dependent signaling in regulating several important factors in cancer progression including tumor proliferation, metastasis, angiogenesis and drug resistance." (PMID 29682217, 2018). "Moreover, leptin and its receptors are over-expressed in different human cancers." (PMID 28861689, 2017). "Thus, obese preadipocyte-, or mature adipocyte-surrounding tumors (also named cancer-associated-adipocytes, CAA) are likely to negatively impact the course of tumor, through increased secretion of leptin or pro-inflammatory cytokines, as demonstrated in human breast cancers." (PMID 28708082, 2017). "Indeed, we speculate that cellular events, i.e., autophagy, ER stress and apoptosis, respond to leptin very differently in normal and cancer cells." (PMID 29250056, 2017). "Adipokines such as leptin and adiponectin, derived from white adipose tissue, are also hypothesized to play direct or indirect opposing roles (leptin unfavorable, adiponectin favorable) mediating cancer cell proliferation, invasion, and survival." (PMID 28620703, 2017). "However, among children survivors of cancer it is not exactly known how and to what extent IR, adiponectin and leptin are associated with each of the components of MS." (PMID 28193268, 2017). "However, administration of OB3 might be able to suppress leptin-stimulated signals and the development of cancers." (PMID 28750624, 2017). "Therefore, the OB3 peptide is a potential anticancer agent that might be employed to prevent leptin-induced cancers in obese people." (PMID 28750624, 2017). "Furthermore, leptin may act as a growth factor, participating in the development of cancer cell lines." (PMID 28316984, 2017). "In addition, a recent study indicated that leptin promotes cancer stem cell survival." (PMID 28399860, 2017).